DCN (decorin)
Diseases named in the same sentence as DCN in open-access papers (continued):
Sharing a sentence is not in itself a finding about the gene and the disease.
tumor (continued). "Recent research has demonstrated that DCN can modulate the tumor microenvironment, thus inhibiting tumor progression by inducing autophagy and apoptosis." (PMID 39145305, 2024). "Decorin regulates multiple aspects of tumor biology, including tumor cell proliferation, migration, and exhibiting both pro-inflammatory and anti-fibrotic effects." (PMID 39845957, 2024). "In this study, we established a CRC model in immunodeficient NPG mice to evaluate the combined therapeutic effect of rAd.DCN and NK cells, as well as the enhanced anti-tumor effect of rAd.DCN on NK cells." (PMID 39482550, 2024). "In GBM, decorin has been shown to decrease matrix stiffness, enhance immunogenicity, induce autophagy of tumor cells, decrease VEGf expression, and mediate microglia infiltration." (PMID 38380331, 2024). "This indicates that DCN downregulation in stromal fibroblasts can activate breast carcinogenesis and enhance the pro-invasive and metastatic potential of BC cells by promoting EMT and stemness." (PMID 38667295, 2024). "This identified multiple genes downregulated in tumour-associated adventitial fibroblasts compared to control counterparts, including IGFBP6, FABP4 and DCN." (PMID 36720863, 2023). "When VEGF and decorin immunostaining classifications were combined, the ability to identify subsets of tumours with very favourable or very unfavourable outcomes was improved." (PMID 37104411, 2023). "Mechanically, we uncovered that B. adolescentis induced Decorin+ macrophages infiltration in TME and Decorin in macrophages was a crucial molecule mediating the anti-tumor effect of B.adolescentis." (PMID 37464382, 2023). "It follows that reduced levels of decorin within a tumour will increase the availability of VEGF and other sequestered cytokines within the tumour microenvironment." (PMID 37104421, 2023). "In one study of human STS, decorin was assessed in 85 different tumours by real-time quantitative PCR and immunohistochemistry." (PMID 37104411, 2023). "Knockdown of Decorin in Raw264.7 was performed to investigate the effect of Decorin+ macrophages on subcutaneous tumor formation." (PMID 37464382, 2023). "DCN possesses a multitude of oncosuppressive functions including growth suppressing, angiostasis, and tumor cells mitophagy arrest." (PMID 37464382, 2023). "Adenoviruses have also been engineered to express proteins like relaxin and decorin which downregulate collagen expression in tumor tissue, enhancing viral spread in the tumor and improving anti-tumor effects." (PMID 38022679, 2023). "Myokines such as oncostatin M (OSM), secreted protein acidic rich in cysteine (SPARC), irisin, and decorin can directly restrain tumor development by blocking cell proliferation and migration and promoting tumor cell apoptosis." (PMID 37958310, 2023). "For the variables decorin, differentiation, mitotic rate, necrosis, grade, age, and tumour size, the AUC was calculated to be between 0.49 and 0.64." (PMID 37104421, 2023). "The interaction of decorin with various receptors in tumor niche exhibits antiproliferative and anti-angiogenic effects, whereas the interplay among biglycan and TLRs induces inflammation." (PMID 36342580, 2023). "We found that TLR2 inhibition reduced the number of DCN+ macrophages in tumor and attenuated tumor suppressive effect of B.adolescentis-treated macrophages." (PMID 37464382, 2023). "Based on these results, four variables: VEGF, decorin, mitotic rate, and age, were used to generate a nomogram to calculate the probability of being tumour-free at 3 years." (PMID 37104421, 2023). "Half of the 50 STS that were less than 5 cm in diameter had a type 3 decorin pattern and this pattern was significantly more frequent in these smaller tumours than in STS that were greater than 5 cm in diameter (3 of 21 (14%); p = 0.02)." (PMID 37104411, 2023).
tumor (continued). "Here we found that in the antitumor activity of OAV-Decorin in immunocompetent mouse, there were increased intratumoral murine IFN-γ proteins and decreased murine TGF-β in OAV-Decorin treated-tumor compared with OAV." (PMID 34977339, 2022). "Decorin target genes were downregulated in the tumor as well as in the metastases, indicating a direct activity of virus-derived decorin on cell signalling." (PMID 35155581, 2022). "For example, decorin (CSPG) is known to have major tumor suppressor effects, while perlecan (HSPG) plays a central role in both physiological and pathological angiogenesis." (PMID 36230789, 2022). "This is further underscored by a recent study demonstrating that decorin is downregulated in senescent fibroblasts, which additively drives the tumor-promoting phenotype of ionizing radiation induced premature senescence." (PMID 35159071, 2022). "Decorin has mostly been known for its tumor-suppressor functions through TGF-β and EGFR-mediated signaling and was previously found to be downregulated in PCa." (PMID 36230789, 2022). "Decorin can also inhibit tumor growth by blocking epidermal growth factor receptor (EGFR) and ErbB4 dimerization." (PMID 36033387, 2022). "It indicated that intratumoral secretion of decorin mediated by oncolytic adenovirus promoted an inflammatory response in the tumor microenvironment and improved tumor control in an immunocompetent mouse model." (PMID 34977339, 2022). "It was found that LOXL2, PLOD2, MMP14 and SPOCK1 were upregulated in tumor samples, whereas DCN was downregulated in tumor specimens." (PMID 36186418, 2022). "Although pro-tumorigenic signals are expected in the tumor environment, some anti-tumorigenic molecules such as decorin can be detected." (PMID 35155581, 2022). "In our evaluation, tumor cells were lysed directly by OAV-Decorin to recruit CAR-T to the tumor site." (PMID 34977339, 2022). "In each case, decorin signals via a unique cell surface receptor tyrosine kinase to evoke autophagy (VEGFR2) or mitophagy (MET receptor) that converges on a novel tumor suppressor gene." (PMID 35159071, 2022). "The intratumoral injection of OAV-Decorin into tumor-bearing immunocompetent mice activated the inflammatory immune status and resulted in tumor regression." (PMID 34977339, 2022). "Initially characterized as a tumor suppressor, we discovered that Peg3 acts as a nexus for decorin- (and other PGs)-mediated autophagy." (PMID 35159071, 2022). "The expression of decorin in tumor-bearing mice treated with OAV-DEC or OAV-DEC + CAIX-CAR-T evidently inhibited the distribution of collagen fibers, which is a major component of extracellular matrix (ECM)." (PMID 34977339, 2022). "Another group analysed the expression pattern of protein DCN in healthy mucosa, primary tumour and liver metastases of CRC." (PMID 35052821, 2022). "It is possible that LUM and DCN play a dual role in the maintenance of CSCs and cell fate which is dependent on the tumor microenvironment (TME)." (PMID 36358747, 2022). "Differential gene analysis revealed 319 genes upregulated in tumor-derived fibroblasts, such as DCN and SFRP4, and 214 genes upregulated in cancer cells, such as SPRR1B and SLURP2." (PMID 36357663, 2022). "In tumors, decorin has been shown to inhibit metastasis, tumor cell proliferation, and angiogenesis and regulate autophagy and inflammation." (PMID 36033387, 2022). "Peg3 was identified from a subset of differentially expressed genes exclusively within the murine tumor stroma of triple negative orthotopic tumor xenografts treated systemically with human recombinant decorin." (PMID 35159071, 2022). "Further studies verify that ASPN expression is low in non-tumor tissues, including breast tissue, on the contrary to DCN and BGN, which present high expression levels in normal tissues." (PMID 36358747, 2022).
tumor (continued). "In order to characterize the effects of oncolytic adenovirus arming decorin (OAV-DEC) on immune response in the tumor microenvironment, we also evaluated its use in an immunocompetent mouse model because human decorin is cross-reactive for mouse cells." (PMID 34977339, 2022). "Decorin has been shown to be involved in wound repair, cell cycle, angiogenesis, tumor metastasis, and autophagy." (PMID 36033387, 2022). "We found that decorin expression was decreased in tumor tissues compared to that in normal renal tissue, while the expression of TGF-β1 did not change significantly." (PMID 35777025, 2022). "It was reported that rAd.DCN inhibited tumour growth and metastasis as a consequence of decorin interfering with wnt/β-catenin, vascular endothelial growth factor (VEGF), the Met pathways and by modulating anti-tumour inflammatory and immune responses." (PMID 35813830, 2022). "Apart from engaging the Met receptor, decorin can attenuate tumor growth as a monomeric proteoglycan." (PMID 34917515, 2021). "Taken together, our findings demonstrate that DCN acts as a tumor- and metastasis suppressor in IBC by accelerating the autophagic degradation of E-cadherin and suppressing activation of EGFR–ERK signaling." (PMID 33452400, 2021). "The result of HE staining showed that U251-shNC tumor or U251-decorin-shRNA tumor tended to invade the neighboring normal tissue, however, the U251-decorin tumor kept a relative smooth edge." (PMID 34386415, 2021). "Collectively, these results indicated that DCN secreted by CAFs functions as a tumor suppressor to inhibit VI of HCC." (PMID 34504839, 2021). "Reportedly, the proteoglycan decorin, secreted by fibroblasts, inhibits tumor growth and can induce the expression of tumor-suppressor genes in the microenvironment surrounding TNBC, thereby restraining tumor metastasis." (PMID 34262865, 2021). "Other few proteins such as Fibulin-2, EMILIN-2, and Decorin, are described also to have tumor suppressive functions." (PMID 34299025, 2021). "Together with decorin, the protein codified by DCN, both proteins are highly involved in the tumour development process." (PMID 34445187, 2021). "More importantly, co-staining DCN and integrin β1 revealed that DCN dynamically regulated integrin β1 protein expression, in that a decrease in DCN was accompanied by integrin β1 upregulation from normal, to primary tumor and PVTT tissues." (PMID 34504839, 2021). "We examined ECM pathways that related to cancer progression to identify downstream targets of DCN for promoting tumor metastasis." (PMID 34504839, 2021). "The interaction of decorin with VEGFR2 constitutes the most significant contribution to impairing tumor angiogenesis." (PMID 34917515, 2021). "The small leucine-rich proteoglycan decorin (DCN) is an important component of the cellular microenvironment and has been shown to inhibit the growth of a wide variety of tumor cells, probably due to an interaction of the decorin core protein with EGFR." (PMID 34283070, 2021). "Although we did not evaluate the other proteoglycans, their concentrations in plasma and tissue should be analyzed since the dysregulation of DCN resulted in the formation of a tumor-supportive microenvironment." (PMID 34884232, 2021). "In this review, we summarize growing evidence for the complex roles of decorin and biglycan signaling in tumor biology and address potential novel therapeutic implications." (PMID 34917515, 2021). "Conversely, multiple independent studies have clearly demonstrated an angiostatic effect of decorin in the setting of cancer and its down-regulation correlates with the degree of tumor vascularization in various cancer types." (PMID 34917515, 2021). "The anti-tumor activities of decorin additionally include the regulation of the autophagy and mitophagy pathways." (PMID 34917515, 2021). "Previous research has shown DCN to be a tumor suppressor in different tumor types, including breast cancer." (PMID 33452400, 2021).
tumor (continued). "On the other hand, DCN-bound TGFβ presumably prevents pathway activation and thereby acts as a tumor suppressor." (PMID 34379688, 2021). "In vivo tumor treatment studies with a recombinant DCN core protein have thereby been carried out with considerable success." (PMID 34379688, 2021). "In tumor cells, decorin inhibits tyrosine kinase receptors, such as epidermal growth factor receptor, type I insulin-like growth factor receptor, and hepatocyte growth factor receptor (or mesenchymal-epithelial transition factor)." (PMID 34212564, 2021). "There are two mechanisms for decorin-dependent control of inflammation and tumor growth that are based on either stimulation of PDCD4 (programmed cell death protein 4) expression, or on it translational repression." (PMID 34917515, 2021). "On the other hand, small leucine-rich proteoglycans like lumican and decorin serve as tumor suppressors by physically antagonizing RTK such as EGFR and c-Met (receptor for HGF), evoking antisurvival and proapoptotic pathways." (PMID 34976811, 2021). "Our study uncovers ASPN as a GC-promoting gene and DCN as tumor suppressor, suggesting that ASPN can act as a prognostic marker in GC." (PMID 34379688, 2021). "Recently, decorin has been established as an autophagic signal transducer by initiating endothelial cell autophagy and by inducing tumor cell mitophagy." (PMID 33924197, 2021). "Other studies have shown that DCN regulates the TGFβ signaling pathway and inhibits the growth of various tumor cells." (PMID 33918979, 2021). "Decorin, the prototype member of the small leucine-rich proteoglycans is a key component of tumor stroma and acts as a tumor suppressor in cancer by down-regulating the activity of several tyrosine-kinase receptors, including the IGF1R and IR-A." (PMID 33673232, 2021). "Direct binding of decorin to the Met receptor results in tumor suppression by phosphorylation of Met tyrosine sites, leading to recruitment of the proto-oncogene CBL (Casitas B-lineage Lymphoma) and subsequent proteosomal degradation of the Met receptor." (PMID 34917515, 2021). "We analyzed correlations between DCN mRNA expression in HCC tumor tissues and clinical pathological characteristics to determine the clinical importance of DCN expression." (PMID 34504839, 2021). "Decorin binds and antagonizes various receptor tyrosine kinases, thereby inhibiting downstream oncogenic signaling and reducing tumor growth." (PMID 34490248, 2021). "In this regard, DCN is considered as a potent natural inhibitor of tumor cell proliferation and invasion, whereas the other proteoglycans, namely, versican and biglycan, are not." (PMID 34884232, 2021). "We established that ECM-related pathways mediated VI by HCC, and that DCN gradually became downregulated from normal to tumor and further in PVTT tissues." (PMID 34504839, 2021). "Here, we investigated the complex interplay of asporin, decorin and their interaction with TGFβ in GC tumor and corresponding normal tissues." (PMID 34379688, 2021). "Among factors participating in tumor diseases pathogenesis are members of small leucine-rich proteoglycans, a family of matricellular proteins: decorin, biglycan, asporin, and lumican." (PMID 34212564, 2021). "For example, decorin, a small leucine-rich extracellular matrix proteoglycan, is well-studied for its role as a suppressor of tumor cell growth." (PMID 34490248, 2021). "Decorin (DCN), an extracellular matrix proteoglycan found in tumor surrounding tissues, is a natural inhibitor of tumor cell proliferation and invasion." (PMID 34884232, 2021). "Emerging evidence has uncovered the pivotal functions exerted by the small leucine-rich proteoglycans, decorin and biglycan, in affecting tumor growth and progression." (PMID 34917515, 2021).
tumor (continued). "DCN suppresses tumor cell-mediated angiogenesis by inhibiting the endogenous production of vascular endothelial cell growth factor, similar to neutralizing antibodies directed toward the epidermal growth factor receptor (EGFR)." (PMID 33918979, 2021). "HRE-Ki67-Decorin suppressed tumor growth and induced decorin expression in the extracellular matrix (ECM) assembly." (PMID 35004284, 2021). "Considering that DCN affects tumor cells mainly via extracellular signaling, we added DCN to culture medium as ectopic expression." (PMID 34504839, 2021). "We demonstrate that the chondroitin polymerizing factor (CHPF), an enzyme that mediates the elongation of chondroitin sulfate (CS), is a critical elicitor of the malignant characteristics of HCC as it modifies the potent tumor suppressor, decorin (DCN)." (PMID 33809195, 2021). "Mechanistically, DCN functioned as a suppressor of invasion and tumor growth in IBC by destabilizing E-cadherin and inhibiting EGFR/ERK signaling." (PMID 33452400, 2021). "We then investigated the expression of TGF-β1, TGF-β2, and receptor tyrosine kinases (HER2), which are signaling molecules involved in DCN-mediated tumor carcinogenesis and metastasis." (PMID 34504839, 2021). "Relationship between the expression of decorin in tumor tissues and clinical characteristics of HCC patients." (PMID 34504839, 2021). "We analyzed the effects of elevated DCN concentrations in culture medium of HCC cell tumor phenotypes to functionally validate the anti-metastatic role of DCN." (PMID 34504839, 2021). "Delivery of the DCN gene reduced tumor formation in a mouse model of hepatocarcinogenesis evoked by thioacetamide." (PMID 34504839, 2021). "DCN is also expressed and secreted by fibroblasts in the stroma where it binds to collagen I stimulatory surfaces to antagonise tumour growth by overcoming TGF-β-mediated immunosuppression, suggesting an important role in stroma-cancer cell communication." (PMID 33889206, 2021). "Compared to the U251-decorin tumor, U251-shNC and U251-decorin-shRNA tumors exhibited clear characteristics of invasion." (PMID 34386415, 2021). "To investigate the function of DCN in IBC tumor growth and progression, we used orthotopic xenograft transplantation of control and DCN-overexpressing IBC cells into the cleared mammary fat pad of immunocompromised SCID/Beige mice." (PMID 33452400, 2021). "Analysis of an IBC patient dataset that contains both IBC tumor cells and tumor stroma (GSE5847) confirms that DCN is expressed in both tumor cells and stroma, with slightly higher expression seen in tumor cells." (PMID 33452400, 2021). "Collectively, these observations posit the small leucine-rich proteoglycan decorin as an important component of the angiostatic network and the cross-talk between and endothelial and tumor cells." (PMID 34917515, 2021). "As a result, the ER+ cancer sample was clustered with ER+ tumor cells (ESR1+, KRT18+, and KRT5−), KRT5+/EPCAM+ double-positive cells, cancer-associated fibroblasts (CAFs) (DCN+), macrophages (CD68+), KRT5+/EPCAM− cells, and endothelial cells (VWF+)." (PMID 34685653, 2021). "Tumor DCN levels in our dataset significantly differed only between subgroups of patients divided by MVI status (yes or no, p = 0.048)." (PMID 34504839, 2021). "ASPN is highly expressed in patient tumor tissues compared to normal tissues, whereas DCN showed opposite pattern of gene expression." (PMID 34379688, 2021). "The levels of E-cadherin and EGFR protein were decreased in the tumor samples from DCN-overexpressing MDA-IBC3 and SUM149 xenografts, as shown by western blotting and immunohistochemical staining." (PMID 33452400, 2021). "We found that DCN gradually decreased during progress from normal to primary tumor and metastatic tissues from the public GSE69164 dataset and in our cohort." (PMID 34504839, 2021).